INS (insulin)
Diseases named in the same sentence as INS in open-access papers (continued):
Sharing a sentence is not in itself a finding about the gene and the disease.
diabetes (continued). "Problems with weight gain, especially in girls, can trigger disordered eating and have significant adverse effects on diabetes control, given that insulin omission is an adaption used commonly to enhance weight loss." (PMID 25791276, 2015). "Nearly half (51.8 %) of patients had duration of diabetes of ≤ 5 years, 28 % were taking insulin therapy, and 93.2 % were on oral hypoglycemic medications." (PMID 26280008, 2015). "Insulin-dependent diabetes mellitus (IDDM) or type 1 diabetes is due to autoimmune destruction of the insulin-producing pancreatic β-cells resulting in an absolute deficiency of insulin." (PMID 25866533, 2015). "Another study showed that insulin-sensitizing drugs reduced omentin levels in newly diagnosed patients with diabetes." (PMID 26466574, 2015). "The choice of initial insulin is often dictated by subjective criteria: the “severity” of diabetes, the ability of the person with diabetes to self inject, at specific times of the day, and the physician’s personal experience." (PMID 25874190, 2015). "Multiple studies have identified elevated production of proinflammatory cytokines, such as TNF-α, IL-1β, and IFN-γ, which can impede insulin signaling in obesity and diabetes." (PMID 26146464, 2015). "In accordance with our results, increased circulating concentrations of Tyr and Phe have often been reported in the obese, insulin-resistant, or diabetes state in humans." (PMID 25821801, 2015). "Though various types of oral hypoglycemic agents are available along with insulin for the treatment of diabetes mellitus so far, many drugs are limited by side effects and toxicity." (PMID 25809611, 2015). "In conventional therapy, insulin-dependent diabetes mellitus or type 1 is treated with exogenous insulin while the non-insulin-dependent diabetes mellitus or type 2 is treated with oral hypoglycemic agents." (PMID 25988523, 2015). "This is considered the early stage of diabetes pathogenesis, and the normal response toward inflammation, before insulin secretion abnormality and insulin resistance are observed (adaptation)." (PMID 26132231, 2015). "Among the dipeptidyl peptidase-4 (DPP-4) inhibitors that are widely used, sitagliptin is the first to be approved for patients with type 2 diabetes mellitus (T2DM) on insulin therapy." (PMID 26124906, 2015). "Two broad categories encompass the majority of diabetes: type 1 diabetes results from the inability to produce and secrete insulin and type 2 diabetes is characterized by a chronic insulin resistance which may be accompanied with a relative deficiency in insulin secretion." (PMID 25873768, 2015). "The patient’s diabetes and anaemia showed a good response to daily thiamine doses, reducing the daily insulin dose requirement." (PMID 25878670, 2015). "In this case, it seems that the treatment of diabetes with UD has reduced blood sugar to its normal level, and had hypoglycemic effect as well as through improving insulin secretion of hyperglycemic rats." (PMID 27047060, 2015). "Most women who have gestational diabetes can successfully control their blood sugar with diet and exercise, while some will require oral diabetes medication or insulin." (PMID 26273667, 2015). "The perturbed production or utilization of cellular insulin leads to the development of type 2 diabetes, which is also known as non-insulin dependent diabetes mellitus." (PMID 26703529, 2015). "Some studies suggest that there is a significant improvement in glucose tolerance and only slight one in insulin secretion in patients with hypertension and diabetes, when treated with guanfacine for one year." (PMID 26506439, 2015). "Subject selection criteria were patients on maximal oral anti-diabetes treatment who needed to commence insulin therapy." (PMID 26913243, 2015).
diabetes (continued). "The criteria identified are similar to the Royal College of General Practitioners National Health Service (RCGP/NHS) Diabetes classification guidelines, which use age at diagnosis <35 years and time to insulin <6 m." (PMID 26525723, 2015). "We defined incident diabetes as fasting plasma glucose level ≥7.0 mmol/L, or the use of oral antidiabetic medication or insulin, or treatment by diet and registered by a general practitioner as having diabetes." (PMID 26386597, 2015). "A major contributing factor to diabetes is the development of insulin resistance in peripheral metabolic organs in which insulin becomes progressively less effective in lowering plasma glucose level." (PMID 25575350, 2015). "Patients showed a low level of knowledge when 28.8% stated that high blood glucose leads to diabetes, and only 20.1% said that diabetes is due to the body’s failure to produce insulin." (PMID 26925888, 2015). "In contrast, type 2 diabetes mellitus represents an insulin-resistant state and manifests in the majority of patients with a metabolic syndrome in the middle or higher age." (PMID 26000307, 2015). "Hyperglycemia in the ICU patient can be treated with exogenous insulin and by the enteral administration of diabetes-specific formulas." (PMID 26549276, 2015). "During the study period, 38 and 47 nurses instructed patients how to use an insulin pen device to naïve or to experienced insulin users with diabetes, respectively." (PMID 28702233, 2015). "Maintainance of a stable basal insulin level is important for glycemic control in treatment of diabetes mellitus." (PMID 26819737, 2015). "Increasing the consumption of a food naturally enriched with CLAt10,c12 significantly worsens glucose and insulin tolerance in a diabetes-prone rodent model." (PMID 26415741, 2015). "miRNAs, such as miR-143-3p and miR-221-3p have been reported to be related to obesity and diabetes, as miRNA-143 inhibits insulin-stimulated AKT activation and impairs glucose metabolism." (PMID 25370776, 2015). "Dysregulation of multiple glucoregulatory hormones (insulin and glucagons) that maintain glucose homeostasis result in the form of diabetes." (PMID 26273663, 2015). "We therefore conducted a systematic review and meta-analysis of RCTs to synthesize the effect of replacing sources of animal protein with plant protein on glycemic control assessed by HbA1c, fasting glucose, and fasting insulin in individuals with diabetes." (PMID 26633472, 2015). "The risk factors that were shown to have significant and independent associations with diabetic retinopathy in the multivariate analysis in this study included age, duration of diabetes and being under insulin treatment." (PMID 25925666, 2015). "Diabetes mellitus is one of the most common serious metabolic diseases that results in hyperglycemia due to defects of insulin secretion or insulin action or both." (PMID 26075247, 2015). "Homeostatic control of blood glucose is regulated by a complex feedback loop between glucose and insulin, of which failure leads to diabetes mellitus." (PMID 26623647, 2015). "Diabetes was assessed by self-report and classified as un-medicated, treated by oral antidiabetic agents or by insulin." (PMID 26010615, 2015). "The interface of nanotechnology in the treatment of diabetes has introduced novel strategies for glucose measurement and insulin delivery." (PMID 26273667, 2015). "Of the 320 respondents, 33 (10.3%) reported having Type 1 diabetes; 107 (33.4%), Type 2 diabetes and taking insulin; and 180 (56.3%), Type 2 diabetes and taking oral agents or controlling their diabetes with lifestyle modifications." (PMID 26126421, 2015). "Odds ratios and 95% confidence intervals for mild and severe hypoglycemia according to each factor in 123 patients with insulin-treated diabetes during the 6-month follow-up period." (PMID 26102197, 2015).
diabetes (continued). "A study from Europe showed that men with parental diabetes are more likely to have impaired insulin sensitivity and beta cell function than women." (PMID 26322779, 2015). "The combination therapy (OA and metformin) was found to possess different but complementary mechanisms of action on the plasma glucose and insulin levels that prevented the development of diabetes." (PMID 25789330, 2015). "Although previous literature has established links between OP pesticide exposure and diabetes biomarkers, we only observed DMDTP to be associated with fasting insulin after adjusting for BMI." (PMID 26366294, 2015). "Oral hypoglycemic agents and insulin, generally used to treat Diabetes Mellitus (DM), have number of serious side effects." (PMID 26020019, 2015). "It is well known that the obesity of those with diabetes tends to ameliorate with advancing age; insulin levels decline with time as beta-cell function fails." (PMID 26250516, 2015). "Diabetes control with insulin was in 333 (21%) patients, 62 (17%) men and 271 (22.4%) women; the difference between the sexes in using insulin was significant (p<0.05)." (PMID 26644897, 2015). "Food intake increased after the induction of diabetes with STZ in all the groups except the rats treated with a high dose of insulin to maintain plasma glucose concentration in the normal range." (PMID 26169541, 2015). "Diabetes mellitus (DM) is a debilitating chronic metabolic disorder featured by hyperglycemia due to defects in insulin secretion, insulin action, or both." (PMID 26682215, 2015). "Diabetes treatment is based on pharmacological hypoglycaemic agents and insulin; however, the efficacy of these therapies is limited due to their many side effects." (PMID 26347893, 2015). "The AKT/PI3K signaling pathway is closely related to the development of diabetes and the mechanism of decreased insulin sensitivity." (PMID 26715102, 2015). "Here, we consider pharmacokinetic (PK) data on insulin aspart, a fast acting insulin analogue used in the treatment of diabetes." (PMID 26013427, 2015). "Adolescents who used insulin pumps reported using more technologies for diabetes on average (B=0.52, SE=0.23, P=.03; beta=.17), as did adolescents of parents who used more technologies for diabetes (B=0.44, SE=0.09, P<.001; beta=.36)." (PMID 26715191, 2015). "The control subjects (n = 40) and people with prediabetes (n = 52) and diabetes (n = 66) were similar in terms of age, sex, BMI, systolic and diastolic BP, and fasting insulin level." (PMID 26078977, 2015). "In this work we demonstrate that the pdx1 mutant zebrafish is a new vertebrate model of diabetes, as fish show the key features of decreased beta cells and insulin, and persistently elevated glucose levels." (PMID 26384018, 2015). "Adjusted* associations of frequency of coffee consumption per day with newly diagnosed diabetes, intermediate hyperglycemia, and insulin levels, from ELSA-Brasil (2008–2012) (N = 12586)." (PMID 25978631, 2015). "Accordingly, medications that rely on insulin secretion are characterized by a high rate of secondary failure and can be used only in the initial phases of diabetes, and most patients will ultimately rely on insulin for glycaemic control." (PMID 25785281, 2015). "Her glucose even reached 1.22 mmol/L while the serum glycosylated hemoglobin was normal and previous history of diabetes or use of oral hypoglycemic agents and insulin denied." (PMID 26496258, 2015). "Currently available therapies for diabetes include insulin and various oral hypoglycemic agents, such as sulfonylureas, biguanides, metformin, glucosidase inhibitors, troglitazone, etc.." (PMID 25988523, 2015). "For example, the transdermal delivery of insulin using microneedles (MNs) fabricated with 15% HA containing insulin is used in diabetes patients." (PMID 26448753, 2015). "Decrease in plasma insulin levels in animal models after STZ application is used a sign for inducement of diabetes." (PMID 27275254, 2015).
diabetes (continued). "Patients who had retired because of diabetes were less likely to use combined insulin therapy than were employed patients [58 (69.9%) vs 1,638 (84.8%), p = 0.0002]." (PMID 25963135, 2015). "For example, the increased insulin resistance to diabetes development is a more prominent factor in Pima Indians, Mexican Americans and Caucasians; whereas the contribution of impaired insulin secretion is a more important factor in Japanese patients." (PMID 25924608, 2015). "The present study clearly shows that multiple markers, including 10- and 12-(Z,E)-HODE/LA, insulin, and leptin/adiponectin, can be used for the early detection of diabetes." (PMID 26132231, 2015). "Gene-word “Insulin” also had a high number of derived keywords that includes insulin resistance, insulin sensitivity, insulin secretion etc. and these derived keywords have the third highest (14.34) average frequency after diabetes (21.99)." (PMID 25915521, 2015). "Diabetes treatment was based on oral antidiabetics (OADs) in 50.9%, insulin in 20.9% and OADs + insulin in 20.9% (Table-I)." (PMID 25878608, 2015). "Recently, the effect of RANKL has been investigated on insulin sensitivity and glucose homeostasis in animal models of insulin resistance and diabetes." (PMID 25873952, 2015). "As a result, hyperinsulinemia elevated the insulin action through these pathways and accelerated the diabetes and other conditions like atherosclerosis." (PMID 26273663, 2015). "In the present study, we observed that the combination therapy with a selective SGLT2 inhibitor, canagliflozin, and an insulin sensitizer, pioglitazone, further improved glycemic control in the KK-Ay mice with established diabetes." (PMID 25615826, 2015). "Diabetic mellitus generates the disordered metabolism of proteins and fats due to inappropriate production of insulin, a blood glucose regulator, or resistance to insulin that results in high blood glucose levels, or hyperglycemia." (PMID 25996677, 2015). "Genes with associated decreased regions were enriched for GO terms related to β-cell function, such as “glucose transport”, “Maturity onset diabetes of the young” and “insulin secretion”." (PMID 26505193, 2015). "The pancreatic β-cells and their secretory product, namely, insulin, are central in the pathophysiology of diabetes." (PMID 25866533, 2015). "The main diagnosis of diabetes mellitus is based on several techniques for measuring the plasma glucose or serum insulin level, confirming that the selection and application of the predictor features requires further attention." (PMID 26156928, 2015). "In a 17 year follow-up of the Bogalusa Heart Study, those with incident prediabetes and diabetes were more likely to have been in the top decile for glucose, insulin and HOMA-IR during childhood." (PMID 25940643, 2015). "Our results show that Zinc plays an important role in β-cell function, insulin action, glucose homeostasis and the pathogenesis of diabetes and its complications." (PMID 26381880, 2015). "MiR-185 plays an important role in the regulation of insulin secretion and β-cell growth in diabetes." (PMID 25658748, 2015). "In the present study, neonatal streptozotocin (STZ)-treated mice were used to model the molecular and physiological progress from insulin resistance to diabetes." (PMID 25799429, 2015). "Most of the patients in our case series ceased insulin therapy and glycemic control remained satisfying, indicating that nonessential prescription of insulin was common in Chinese patients with diabetes." (PMID 25961056, 2015). "The development of new compounds for treating diabetes is currently important to reduce the need for insulin injection in diabetic patients and to replace the clinically used synthetic therapeutics, which has several severe side effects." (PMID 26381880, 2015). "Differences in insulin secretion measured by C-peptide level between these types of diabetes were already reported by some researchers." (PMID 25916214, 2015).
diabetes (continued). "Exogenous insulin treatment for diabetics includes animal insulin, human insulin and insulin analogues." (PMID 26242987, 2015). "Diabetes implications: Tesofensine has been found to have beneficial effects on plasma insulin and HbA1c concentrations." (PMID 25894803, 2015). "Weight loss enabled one participant with obstructive sleep apnea to cease treatment with continuous positive airways pressure and another with diabetes to have a reduction in insulin." (PMID 25709598, 2015). "Insulin forms an essential requirement for type 1 and type 2 advanced diabetes and the traditional systems of insulin delivery included infections, painful administration, and poor compliance of patients." (PMID 26273667, 2015). "Igf2 transcription is defective in the thymus of diabetes-prone bio-breeding rats, and tolerance to insulin is severely decreased in Igf2−/− mice." (PMID 26175734, 2015). "With the growing number of patients with T2DM, including those on insulin therapy, the diabetes convention more and more suffered from its historical weaknesses." (PMID 26171143, 2015). "The available therapies for diabetes include insulin and oral antidiabetic agents such as sulfonylureas, biguanides, and α-glycosidase inhibitors." (PMID 26345313, 2015). "The general diabetes knowledge of community pharmacists in Libya was found worse than their knowledge regarding insulin therapy." (PMID 26396963, 2015). "Recently, in the context of ongoing research into the pulmonary safety of inhaled insulin, the effects of diabetes on pulmonary function has also become a subject of interest." (PMID 26185997, 2015). "Diabetes mellitus (DM) is characterized by hyperglycaemia, resulting from defects in insulin secretion, insulin action, or both." (PMID 26064993, 2015). "Therefore, a link between the dose–response parameters of insulin use might also reflect a link with progressive pathophysiological changes associated with increasing diabetes duration such as insulin resistance, inflammation, oxidative stress, and aggravated hyperglycemia." (PMID 26537234, 2015). "For the diabetes-related variables, 43.8% used insulin and the mean baseline fasting blood glucose was 8.4 mmol/L." (PMID 26056618, 2015). "Earlier studies suggest that the best way to treat diabetes is to provide exogenous insulin level according to the blood glucose level of the patient." (PMID 26498972, 2015). "The continuous glucose monitoring (CGM) system is a very useful tool in the management of patients with insulin-treated diabetes, particularly type 1 diabetes (T1D)." (PMID 25916214, 2015). "Before the diagnosis of PNH, he had an almost ten-year past history of diabetes mellitus (DM), which had been well controlled by insulin therapy (glycoalbumin 18–21%)." (PMID 26124968, 2015). "A nurse-managed protocol focusing on carbohydrate intake reduced the incidence of hypoglycemia in patients with diabetes receiving subcutaneous insulin in hospital." (PMID 25961051, 2015). "A recent study compared 18 post-surgical patients (9 with diabetes) receiving either intravenous GLP-1 at 1.5 pmol/kg/min or normal saline along with an insulin infusion for glucose control." (PMID 28702223, 2015). "Morbidly obese patients and patients with diabetes have a lower expression of PPARγ2 mRNA in comparison with morbidly obese insulin sensitive patients, both in VAT and muscle." (PMID 25922847, 2015). "We studied the effects of streptozotocin-induced diabetes (60 mg/kg) on the body temperature rhythm of Wistar rats and the possible modifications resulting from early and late treatments with insulin (6U/day) and/or melatonin (daily 0.5 mg/kg)." (PMID 25960780, 2015). "The main mechanisms suggested to account for early diabetes resolution after bariatric surgery include increased hepatic insulin sensitivity due to energy restriction and improved beta cell function." (PMID 25631620, 2015).